FOXP3 (forkhead box P3)
Diseases named in the same sentence as FOXP3 in open-access papers (continued):
Sharing a sentence is not in itself a finding about the gene and the disease.
tumor (continued). "Specifically, they found decreased infiltration of FOXP3+, CD68+, and PD1+ cells in para-tumor TLS." (PMID 38116013, 2023). "The most recent studies showed that FOXP3+ is a marker of CD8 + T-cell completely exhausted and it is entirely induced by the tumor immune microenvironment which can strongly indicate that the immunosuppressive domestication of CD8+T cells by a certain tumor cell subpopulation." (PMID 38066053, 2023). "Here, we show that the Kindlin-1-dependent regulation of IL-6 secretion controls the differentiation of CD4+ T cells into FoxP3+ Tregs and the ability of Tregs to suppress CD8+ T cell proliferation in vitro, while also regulating Treg numbers in the tumor microenvironment." (PMID 36883731, 2023). "Generally, Tregs‐specific Foxp3 is indispensable for immune system homeostasis and protects Tregs identity in response to abnormal signals, whereas elevated Foxp3+ Tregs level showed a negative correlation with prognosis in various tumor types." (PMID 36226375, 2023). "In tumor-bearing BL23-fed mice, a negative correlation between local Foxp3 levels and tumor size and T-cells subpopulations has been described." (PMID 36611977, 2023). "III regulatory T cells in FoxP3+ regulatory T cells in tumor tissues was not statistically significant (P=0.343 and P=0.322, respectively)." (PMID 36960042, 2023). "Genetic ablation of Klf5, FZU00,004 (a KLF5 inhibitor) and CEL failed to reduce the frequency of tumor-infiltrating Tregs (Cd4+Cd25+Foxp3+ T cells), but Klf5 depletion increased the number of Cd3+Cd8+ T cells and increased the Cd3+Cd8+/Treg ratio." (PMID 36923542, 2023). "Analysis of treated tumors demonstrates that targeting of a Toll-like receptor 7 agonist inhibits Treg expression of FOXP3, PD-1, CTLA4, and HELIOS, resulting in 40-80% reduction in tumor growth and repolarization of other tumor-infiltrating immune cells to more inflammatory phenotypes." (PMID 37928524, 2023). "In the present study, regardless of tumor subtype, patients with an abundance of FoxP3-positive lymphocytes in TME experienced worse benefit from monotherapy with PD-1 inhibitors, suggesting that FoxP3 is a predictive factor for treatment with ICIs." (PMID 36980787, 2023). "We did not differentiate between intratumoral and peritumoral FoxP3+ Tregs, an important distinction for tumor immunity." (PMID 38115302, 2023). "In addition, we discovered that FOXP3 and TIGIT are expressed at higher levels in HNSCC patients by analyzing the TCGA tumor bulk dataset." (PMID 38096229, 2023). "Forkhead box P3 (Foxp3) is a key regulator of the development and function of Tregs, leading to the inhibited expression of granzyme B in CD8+ T cells, thereby impairing the ability of CD8+ T cells and CTLs to destroy tumor cells." (PMID 37753074, 2023). "Moreover, CTLA-4 expression on conventional CD4+(CD8−)CD25+FOXP3+ Tregs was substantially downregulated by SDT – by two-fold in both target and off-target tumours (large effect size for both)." (PMID 36319895, 2023). "Furthermore, in the primary tumor, the percentage of regulatory T (Treg, CD4+Foxp3+) cells is greatly reduced by the ICIE treatment." (PMID 36693842, 2023). "HIV+ samples had higher PD-L1 expression rates in tumour tissue (51% vs. 8% p <0.0001) and displayed denser intratumoural CD4+/FOXP3+ (p <0.0001), CD8+/PD1+ (p <0.0001), with lower total peritumoural CD4+ (p <0.0001) and higher peritumoural CD8+/PD1+ (p <0.0001)." (PMID 37274775, 2023). "This tolerogenic FoxP3/GARP/TGFβ axis, therefore, favors tumor immune evasion." (PMID 37719444, 2023). "One study found that TIGIT is particularly abundant on TILs and explicitly identifies the most nonfunctional CD8+ T-cells and FOXP3+ Tregs in mouse tumor tissue." (PMID 37835436, 2023).
tumor (continued). "Overall, this review will help researchers to understand the advances in the immune-suppressive mechanisms of Tregs, the post-translational regulations of Foxp3, and the potential therapeutic targets and strategies to target the Tregs in TME to improve anti-tumor immunity." (PMID 37936703, 2023). "Furthermore, adenosine-A2AR signaling also promotes the induction of Foxp3+Treg cells from the CD4+Foxp3− T cells that suppress effector T cell-mediated anti-tumor responses, promoting tumor progression." (PMID 37834375, 2023). "Previous research indicated that GARP expressed in tumor cells induced the activation of latent TGF‐β, and hence, matured TGF‐β could upregulate the expression of Foxp3 which rendered effector T cells immune‐suppressive." (PMID 37719444, 2023). "FOXP3 expression in the cytoplasm of tumor cells was of no prognostic significance; however, a high infiltration of FOXP3+ lymphocytes accompanied by a cytoplasmic FOXP3+ tumor was the most detrimental phenotype." (PMID 37835488, 2023). "In this study, Abrine and anti-PD-1 antibody were used to treat Hepa1-6 xenograft mice, results showed that both inhibited the expression of CD47 and PD-L1 in tumor tissues of mice, increased the levels of CD4+ and CD8+ T cells, decreased the level of Foxp3+ Treg cells." (PMID 37334368, 2023). "CD8+, FOXP3+ and PD1+ T-cells were evaluated within tumor cell nests, adjacent or distant stroma." (PMID 38134458, 2023). "Furthermore, As-T combination therapy also significantly reduced the amount of CD223+ and CD279+ on intra-tumor CD8+T cells, and CD4+FOXP3+ Treg cells." (PMID 38161697, 2023). "CD8 Tex with elevated expression of multiple inhibitory receptors (PDCD1, CTLA4, LAG3, TIGIT, HAVCR2) and Tregs with high expression levels of FOXP3, TIGIT, and CTLA4 were enriched in the ESCC TME, which contributed to tumor immune escape and immunotherapy resistance." (PMID 37187751, 2023). "An ongoing phase I trial (NCT03618654) investigating the effect of metformin in combination with durvalumab for head and neck squamous cell carcinoma reported a significant decrease in FOXP3 Tregs and an increase in CD8+ cellular density in the stroma adjacent to the tumor." (PMID 37180129, 2023). "To investigate the spatial contexture of the TME, we used a mIF panel in 95 tumours to focus on CD8+ T cells, FoxP3+ Treg cells, and CD163+ M2-macrophages, and single-stain IHC of PD-L1, which have been shown to influence therapy response and outcomes in OAC patient subgroups." (PMID 37965317, 2023). "Conversely, tissue areas A2 and A3 displaying FOXP3 + regulatory T cells and CD8 + T cells with high PD-1 protein levels interacting with tumor cells were strongly associated with no recurrence, indicating “inflamed” or “hot tumors”." (PMID 36959234, 2023). "Furthermore, the percentages of tumor-infiltrating Foxp3+ Tregs and the levels of CD25 and GITR in tumor-infiltrating Foxp3+ Tregs from Usp47fl/flYthdf1fl/flFoxp3-Cre mice were higher than those from Usp47fl/flFoxp3-Cre mice." (PMID 37788092, 2023). "In LUAD, multiple T-cell subsets (CD8+, CD45RO+, CD8+CD45RO+ and CD4+FoxP3+) showed closer proximity to tumour cells than in LUSC, which exhibited closer distances from tumour cells to T-cells expressing LAG-3, OX40 and TIM-3, and B-cells expressing OX40 and LAG-3." (PMID 37835491, 2023). "Quantification of MYC intensities in tumor cells and densities of immune cell types in consecutive slides revealed a significant negative correlation between MYC expression and infiltration of CD3+, CD4+, FOXP3+, pSTAT1+, and MHCII+ immune cells." (PMID 37642941, 2023). "Collectively, these data indicate that CD8+ T cell-restricted peptides originating from self-tumor antigens like hTERT and WT-1 activate not only self-reactive CD8+ T cells but also are likely to cross-activate CD4+ T cells, including Foxp3+ Treg cells with self-reactive TCRs." (PMID 37761976, 2023).
tumor (continued). "In addition, ICOSLG was positively correlated with Foxp3+ cells and negatively correlated with CD4+ T cells, indicating that ICOSLG is closely related to the immunosuppressive process in the tumor microenvironment." (PMID 37842091, 2023). "Moreover, metformin combined with platinum-based chemotherapy drugs significantly decreases CD4+ FOXP3+ Treg and CD4+/FOXP3− T helper cells in the tumor stroma of patients with advanced-stage EOC." (PMID 37686159, 2023). "Tumour biopsies showed increasing numbers of tumour infiltrating CD4+ and CD8+ lymphocytes, indicating an immune response, as well as persistently low numbers of FOXP3+ Treg, indicating decreased immune suppression within the TME." (PMID 37686020, 2023). "Analysis of CD4 and FoxP3 staining showed that neither docetaxel monotherapy nor docetaxel + NHS-IL-12 combination therapy altered Treg frequency in the tumor." (PMID 37166485, 2023). "Mirroring the conditions during tumor initiation, low number of CSCs could successfully generate CD4+CD25+FOXP3+ Treg cells from infiltrating CD4+ T lymphocytes in a contact-independent manner." (PMID 38038865, 2023). "IHC stain of CD8+ TILs, tumor-infiltrating FOXP3+ Tregs, E-cadherin score, and vimentin score was not different between these two groups." (PMID 37340370, 2023). "In tumor-infiltrated Treg cells, metformin inhibits FOXP3 expression in an AMPK-dependent manner through the activation of mTORC1, which acts as a negative regulator for FOXP3 induction in naive CD4+ T cells." (PMID 37686159, 2023). "To understand whether the FoxP3 expression in tumor cells affects the RCC microenvironment, we analyzed the high-throughput RNA sequencing data in 786-O cells compared with silencing FoxP3 in 786-O cells." (PMID 37569676, 2023). "As one of the most important players in the tumor microenvironment, tumor-infiltrating lymphocytes consist primarily of CD4 helper cells, CD4 cells, CD25 helper cells, regulatory T cells of the FOXP3 phenotype (Treg), and effector cells such as natural killer cells and CD8+ T cells." (PMID 36936412, 2023). "In comparison, there were no significant changes in the density of tumour-infiltrating FoxP3+CD25+ Tregs." (PMID 37433774, 2023). "Accordingly, in our study, the expression of VISTA, as well as FOXP3, was lower in tumor regions of responders relative to non-responders." (PMID 37153589, 2023). "This study investigated differences in clinical and pathological parameters as well as differences in the tumor immune microenvironment by immunohistochemical examination of tumor infiltration of CD4+, CD8+, FoxP3+, and CD1a+ cells in SD and NSND OSCC patients." (PMID 37345025, 2023). "In the tumor stroma compartment, only higher cell densities of CD8 showed a significantly improved response to nCRT (p = 0.026, linear‐by‐linear trend test); however, a similar trend was seen for high FOXP3+ and PD‐1+ TAIC density in low TRG." (PMID 34743329, 2022). "GP may reduce the expression of FOXP3 and upregulate the ratio of Th1/Th2 in the serum, reducing the ratio of Tregs in the TME of H22 tumor-bearing mice and thus inhibiting tumor growth." (PMID 36235242, 2022). "Since alterations in the immune cell composition and distribution in tumor sites are closely related to activation of CTLs, we evaluated the population and distribution of human CD8+ cells and human Foxp3+ cells in xenografted tumors by performing IHC analysis." (PMID 36358638, 2022). "FOXP3 also acts as a target of ASF1B, which could be involved in tumor immune escape and tumor cell proliferation." (PMID 35174076, 2022). "The CD8+:FOXP3+ ratio may be a more functional measure of anti-tumor immunity and a better indicator of ICI responsiveness compared to CD8+ and FOXP3+ measurements alone." (PMID 35547873, 2022).
tumor (continued). "Although the prognostic value of Foxp3+ Tregs in COAD is controversial, some studies have shown that the role of Treg cells in the tumor microenvironment is unclear and that Tregs may play a role in promoting antitumor immunity." (PMID 36158119, 2022). "In a mouse lung tumor model, inhibition of Arg-1 in myeloid cells diminished growth of established tumors by increasing T-cell infiltration into the tumor tissue, which was accompanied by a significant increase in the CD8/Foxp3 ratio and IFN-γ production in T cells isolated from the tumors." (PMID 35092727, 2022). "Furthermore, PBLs from patients with MPC showed a greater proportion of CD4+CD25+FOXP3+ Tregs, exhausted CD8+CTLA4+ T cells, CD8+CD122+ T cells, and CD8+CD45R+ T cells, which can be regarded as tumor-promoting cells, than in patients with BPC." (PMID 36333670, 2022). "We observed an induction of IL-9 production by tumor infiltrating lymphocytes (TIL) and a subset of FoxP3+ regulatory T cells in the tumoral region of NSCLC patients and identified tumor infiltrating T cells, FoxP3+ Treg cells and tumor cells as IL-9R expressing target cells for IL-9 signaling." (PMID 35514957, 2022). "FOXP3 regulates the expression and infiltration of ENTPD1 to promote the occurrence of tumours." (PMID 36160018, 2022). "Conversely, nonresponding patients had higher levels of FoxP3+ Tregs and reduced numbers of tumor infiltrating CD8+ T cells." (PMID 35790025, 2022). "Conversely, the patients in which there was no tumor FoxP3 expression and elevated Treg count had significantly worse overall and relapse-free survival." (PMID 35874749, 2022). "FOXP3-expressing Treg cells, mostly represented by CD4+ T cells that express CD25 (IL-2 receptor α-chain), are important for controlling self-tolerance and immune homeostasis, but also suppress antitumor immune responses and favor tumor progression." (PMID 35954312, 2022). "Changes to levels of FoxP3+ and MKi67+CD8+ cell densities between baseline (BL) and on treatment (OT) tissue samples provide an early signal of anti-tumor activity and can validate the hypothesized mechanism of action." (PMID 35558070, 2022). "Additionally, HPV-positive lymph node metastases revealed higher percentages of CD163+ TAM and FoxP3+ Treg cells detectable within a 20 μm radius from CTL in both stroma and tumor areas." (PMID 36123711, 2022). "Specifically, although the pro-inflammatory tumor infiltrate is not directly assessed, we do detect increased levels of FOXP3 within cSCC samples." (PMID 35223500, 2022). "On the other hand, CD4+ regulatory T cells (Tregs), which are characterized by their immune-suppressive activity and by the expression of the transcription factor forkhead box P3 (FOXP3), play a pivotal role in promoting tumor progression by suppressing effective antitumor immunity." (PMID 35267528, 2022). "Tim-3 can induce a tumor microenvironment dominated by immunosuppression by functional suppression and exhaustion of T cells and synergistic expressions of Foxp3, CTLA-4, and other harmful immunoregulatory molecules to further attenuate the function of T cells in tumor-killing." (PMID 35958924, 2022). "Regulatory T cells (Tregs), expressing CD25 and forkhead boxP3 (FoxP3), were negative during immune surveillance, resulting in tumor tolerance." (PMID 36299502, 2022). "In addition, CD4+FOXP3+ regulatory T cells activated the CD39/ENTPD1 pathway and promoted hepatic metastatic tumor growth in mice." (PMID 36185217, 2022). "However, when densities of FoxP3+ and CD163+ cells were jointly considered, either in the tumor center or the invasive margin, the statistical difference was improved." (PMID 36551693, 2022). "By contrast, no change was seen in the proliferation of tumor-infiltrating NK cells or Tregs, and the proliferation of FoxP3- CD4+ T cells increased in βA-secreting tumors." (PMID 35580932, 2022). "Tumour cells induce DCs to secrete TGF‐β and stimulate FOXP3+/CD4+/CD25+ Tregs proliferation." (PMID 36305631, 2022).
tumor (continued). "We also observed a significant decrease in Foxp3 mRNA levels in tumor tissues, but no other significant changes were seen for the other molecules studied." (PMID 35548349, 2022). "It is plausible that the PD-1 blockade induced conversion of CD25+Foxp3+ CD4 Tregs into CD25−Foxp3+ CD4 Tregs38, since we observed the intratumoral transferred CD25+Tregs with PD-1 blockade had decreased tumor egress, along with increased conversion to IFNγ-producing CD25-Tregs." (PMID 35449134, 2022). "Using scRNAseq data from patient samples of primary and recurrent GBM (GSE154975), we identified multiple cell types based on markers from the original study: macrophages (ITGAM), T cells (CD3E), Tregs (CD4, CD3E, FOXP3), low-reads/dying cells (MALAT1), and tumor/normal brain cells (GFAP, SOX2)." (PMID 36591276, 2022). "In addition to the lymphoid lineage markers including CD3, CD4, CD8, CD20, CD45, CD56, and FOXP3, we also examined myeloid lineage markers such as CD14, CD68, CD34 to accurately identify the specific cell types within the tumor microenvironment of YTMA-76." (PMID 35810563, 2022). "Furthermore, we evaluated the relationship between these ratios and the GPS and survival rates and immunohistochemical results of tumor-infiltrating CD3+, CD8+, and Foxp3+ lymphocytes." (PMID 35915403, 2022). "Representative immune markers were used to describe the infiltration levels of immune cells in the tumor microenvironment, for example, CD4+ T cells (CD3, CD4), nTregs (CD4, FOXP3), CD4+ naïve cells (CD4, CD45RA), exhausted cells (CD3, PD-1), and central memory T cells (CD45RO)." (PMID 36032097, 2022). "Interestingly, the close association of the DTL gene and markers of Treg cells and T cell exhaustion, such as FOXP3, CCR8, STAT5B, PD-1, CTLA4, and LAG3, was found after adjusting the correlation values for tumor purity." (PMID 35392073, 2022). "One interesting phenomenon we noticed is that C11-Tregs-FoxP3 cluster were more abundant in non-MPR tumor lesions, indicating their aggregation suppressed the immune response induced by neoadjuvant chemoimmunotherapy in non-responder patients." (PMID 35831283, 2022). "The expression of FOXP3 in 15 tumor tissues of GC patients was obviously higher than that in normal tissues." (PMID 36235242, 2022). "Since previous studies have reported that low ratios of Foxp3+ regulatory T cells (Tregs) to either CD3+ or CD8+ T cells were correlated with better prognosis for patients with HCC, the levels of each cell types was assessed in ROCK1wt and ROCK1nc HCC tumours." (PMID 36497425, 2022). "However, analysis of CT26 tumor-infiltrating immune cells demonstrated a significant decrease in regulatory T cells (CD3+; CD4+; FOXP3+) when RXC004 was combined with anti-PD-1 treatment over control or either monotherapy." (PMID 36922934, 2022). "These novel CD4+CD69+FOXP3− Tregs accounted for the vast majority of tumor‐infiltrating Tregs compared with FOXP3+ Tregs and could suppress the CD4+ T‐cell response mainly through mTGF‐β1,145, 146 which was correlated with tumor progression." (PMID 35474948, 2022). "As indicated in these reports, mesenchymal marker expression increased, the infiltration of suppressive immune cells in the tumor microenvironment, including CD3+ CD8+ PD-1+ T cells, CD4+ FOXP3+ Tregs, and M2 macrophages, increased, and the infiltration of cytotoxic T cells decreased." (PMID 35463314, 2022). "However, immunohistochemistry revealed that AXL inhibition reduced the number of Foxp3+ Tregs (cells/mm2) that infiltrated tumor tissues in both the TC1 and C3PQ tumor models (*p<0.05)." (PMID 35356198, 2022). "The prognostic value of intraepithelial FoxP3+ T cell densities also changed from negative to positive comparing “immune-desert” and “inflamed” tumours, but this relationship was less pronounced than in stromal FoxP3+ T cells." (PMID 35140715, 2022).